CDCA5 (cell division cycle associated 5)
Description:
Regulator of sister chromatid cohesion in mitosis, stabilizing cohesin complex association with chromatin. May antagonize the action of WAPL which stimulates cohesin dissociation from chromatin. Cohesion ensures that chromosome partitioning is accurate in both meiotic and mitotic cells and plays an important role in DNA repair. Required for efficient DNA double-stranded break repair.
Synonyms: SORORIN
Tractability: PROTAC: UniProt records ubiquitination sites on it; ubiquitination databases record sites on it.
Gene: Protein-coding gene on chromosome 11 (65,066,300 to 65,084,164, reverse strand). Ensembl gene ENSG00000146670.
Subcellular location: Nucleus; Chromosome; Cytoplasm
Subcellular location (Human Protein Atlas): Nucleoplasm
Pathways (Reactome):
Cell Cycle: Establishment of Sister Chromatid Cohesion; Resolution of Sister Chromatid Cohesion; Separation of Sister Chromatids
Gene Ontology:
Molecular function: protein binding; protein-containing complex binding; chromatin binding
Biological process: double-strand break repair; mitotic sister chromatid cohesion
Cellular component: nucleoplasm; chromatin; chromosome; chromosome, centromeric region; cytoplasm; cytosol; nucleus
Genetic constraint (gnomAD): Loss-of-function variants: 14 observed, 24.87 expected, observed/expected ratio (o/e) 0.56, 90% interval 0.37 to 0.88. The upper end of that interval is the gene's LOEUF score, 0.88, which puts it in group 3 of 6, group 1 being the genes least tolerant of losing a copy. Missense variants: 307 observed, 316.41 expected, observed/expected ratio (o/e) 0.97, 90% interval 0.88 to 1.07. Synonymous variants: 127 observed, 127.13 expected, observed/expected ratio (o/e) 1, 90% interval 0.86 to 1.16.
Homologues: Orthologues: chimpanzee CDCA5 (96% identical), macaque CDCA5 (96% identical), rabbit CDCA5 (76% identical), pig CDCA5 (75% identical), guinea pig CDCA5 (74% identical), mouse Cdca5 (70% identical), dog CDCA5 (70% identical), rat Cdca5 (60% identical), tropical clawed frog cdca5 (38% identical), zebrafish cdca5 (28% identical).
Diseases named in the same sentence as CDCA5 in open-access papers:
CDCA5 is named in the same sentence as 58 diseases in open-access papers, as found by Europe PMC text mining. Sharing a sentence is not in itself a finding about the gene and the disease. The quoted sentences say what the papers report.
breast carcinoma (20 papers, 2015 to 2025). "For instance, CDCA3 has been implicated in promoting proliferation and metastasis in breast cancer by regulating the cell cycle, while CDCA5 has been shown to enhance chemoresistance and tumor growth in ovarian cancer." (PMID 39924497, 2025). "Consistently, we revealed that upregulation of CDCA5 was associated with tumor size and tumor metastasis in breast cancer patients, as well as the poor survival." (PMID 38978058, 2024). "Meanwhile, the AUC value of CDCA5 on breast cancer prediction was 0.987, indicating that CDCA5 was an effective early diagnostic biomarker." (PMID 37287817, 2023). "Meanwhile, CDCA5 has been linked to increased proliferation, invasion, and migration of breast cancer cells, which was also associated with worse clinical features." (PMID 37287817, 2023). "Subsequently, we attempted to investigate the underlying biological function of CDCA5 in breast cancer." (PMID 37287817, 2023). "Meanwhile, CDCA5 has been linked to increased proliferation, invasion, and migration of breast cancer cells, as well as inferior clinical outcomes." (PMID 37287817, 2023). "We found that CDCA5 was expressed at a higher level in breast cancer tissues and cell lines, and overexpression of CDCA5 was significantly associated with poor prognosis of patients with breast cancer." (PMID 38978058, 2024). "In summary, we identified that CDCA5 was significantly upregulated in breast cancer and it predicted poor survival of breast cancer patients." (PMID 38978058, 2024). "Recent investigations have shown the significant involvement of CDCA5 in facilitating the proliferation of several cancer types, including breast cancer, liver cancer, and prostate cancer." (PMID 38539247, 2024). "Mechanistically, we found that CDCA5 promoted the binding of E2F transcription factor 1 (E2F1) to FOXM1 promoter, and Wnt/β-catenin signaling was required for CDCA5 induced development of breast cancer." (PMID 38978058, 2024). "The results of IHC staining indicated that expression of CDCA5 in breast cancer was higher than that in para-carcinoma tissues." (PMID 38978058, 2024). "Herein, we showed the upregulation of CDCA5 in breast cancer, and we used shRNA-mediated knockdown of CDCA5 to explore functional role of CDCA5 in breast cancer." (PMID 38978058, 2024). "Especially, CDCA5 promoted proliferation, migration and inhibited apoptosis of breast cancer cells, which was alleviated by silencing FOXM1." (PMID 38978058, 2024). "CDCA5 function in breast cancer was explored in CDCA5-overexpressed/knockdown cells and mice models." (PMID 38978058, 2024). "To identify the potential CDCA5-targeted genes that were involved in the malignant behaviors of breast cancer cells, we observed the DEGs between shCDCA5-transfected and shCtrl-transfected MDA-MB-231 cells by human Gene Chip Prime View analysis." (PMID 38978058, 2024). "In an agreement, we confirmed that CDCA5 was significantly overexpressed in human breast cancer tissues and cell lines as compared with corresponding controls." (PMID 38978058, 2024). "However, the underlying mechanism by which how CDCA5 facilitates breast cancer remains unclear." (PMID 38978058, 2024). "Collectively, these results suggested that CDCA5 knockdown dramatically inhibited the malignant proliferation, colony formation and migration capacities of breast cancer cells in vitro, while promoted cell apoptosis." (PMID 38978058, 2024). "Taken together, these data suggested that CDCA5 facilitated malignant behaviors of breast cancer cells via promoting the binding of E2F1 to FOXM1 promoter." (PMID 38978058, 2024). "Altogether, these results indicated that Wnt/β-catenin signaling pathway served as the possible downstream of CDCA5 in breast cancer development." (PMID 38978058, 2024). "Firstly, we identified the expression of CDCA5 in human breast cancer tissues by IHC analysis of clinical breast cancer (n = 96) and para-carcinoma tissues (n = 22)." (PMID 38978058, 2024).
breast carcinoma (continued). "The correlation between CDCA5 expression with clinicopathological features and prognosis of breast cancer patients was analyzed using a tissue microarray." (PMID 38978058, 2024). "Representative pictures of both mice and tumor tissues indicated that FOXM1 knockdown impaired tumor growth of breast cancer cells induced by CDCA5 in vivo, which was validated by results of tumor weight." (PMID 38978058, 2024). "Consistently, CDCA5 expression was upregulated in various breast cancer cell lines, especially in BT-549, MDA-MB-231 and MCF-7 cells, compared to the normal MCF-10 A cells." (PMID 38978058, 2024). "CDCA5 was also discovered to be increased in breast cancer cell lines when compared to normal MCF-10A cells." (PMID 37287817, 2023). "The findings demonstrated that breast cancer tissue had a greater CDCA5 protein level than normal tissue." (PMID 37287817, 2023). "Meanwhile, we obtained the immunocytochemistry image to assess the protein level of CDCA5 in breast cancer and normal tissue." (PMID 37287817, 2023). "GSEA analysis revealed that in breast cancer patients with elevated CDCA5 expression, the PI3K/AKT/mTOR pathway was abnormally activated." (PMID 37287817, 2023). "For instance, CDCA5-knockdown inhibited cell proliferation, migration, and clone formation in breast cancer." (PMID 36741311, 2023). "CDCA5 was found to increase the proliferation, invasion, and migration of breast cancer cells in subsequent studies." (PMID 37287817, 2023). "Then, CDCA5 was found to increase the proliferation, invasion, and migration of breast cancer cells in subsequent studies." (PMID 37287817, 2023). "The result showed that the area under the curve (AUC) value was 0.987, indicating that CDCA5 has an extremely great prediction efficacy on breast cancer carcinogenesis." (PMID 37287817, 2023). "Overall, our findings suggest that CDCA5 is a potential prognostic indicator and target for breast cancer, which can indicate the direction of the relevant research." (PMID 37287817, 2023). "CDCA5 was shown to greatly increase the proliferation, invasion, and migration of breast cancer cells in vitro." (PMID 37287817, 2023). "CDCA5 was found to dramatically boost the paclitaxel and docetaxel sensitivity of breast cancer patients in drug sensitivity studies." (PMID 37287817, 2023). "To summarize, this is the first study that thoroughly investigated the role of CDCA5 in breast cancer." (PMID 37287817, 2023). "Genes extracted from the gene expression omic dataset that play key roles in the development of breast cancer are CDCA5, IL17RB, MUC2, NOD2, and NXPH4." (PMID 35205681, 2022). "In this study, we found CDCA5 overexpression dramatically decreased the survival probability of breast cancer patients to lower that 0.5 in the three-year survival rate." (PMID 29467944, 2018). "The CDCA5 mRNA expression level in breast cancer tissue was the highest in the invasive ductal breast carcinoma subtype, with a 5.5-fold change relative to the control tissue." (PMID 29467944, 2018). "A high expression level of CDCA5 was correlated with a shorter RFS in breast cancer patients overall." (PMID 29467944, 2018). "This highly expressed of CDCA5 gene results in a poor prognosis value for breast cancer patients, with an HR of 1.46, and it significantly reduced patient survival over the 3-year and 5-years interval." (PMID 29467944, 2018). "Noteworthy, the CM1 list revealed a set of probes for which little literature exists in relation to breast cancer subtypes: CDCA5, CCL15, COL17A1, GLYATL2, ROPN1, LINC00993 and C6orf211." (PMID 26132585, 2015). "Furthermore, the data of in vitro and in vivo revealed that depletion of FOXM1 alleviated the effect of CDCA5 overexpression on breast cancer." (PMID 38978058, 2024). "The CDCA5 protein enhanced migration and invasion in cellular investigations, aligning with the findings from the sequencing experiments in a study showing the metastatic nature of breast cancer." (PMID 38539247, 2024).
breast carcinoma (continued). "CDCA5 expression was identified through immunohistochemistry staining in breast cancer specimens." (PMID 38978058, 2024). "Importantly, CDCA5 expression was also found to be upregulated in patients with breast cancer and the breast cancer cell lines." (PMID 38978058, 2024). "Moreover, recent studies suggested that overexpression of CDCA5 was an indicator of poor prognosis of patients with hepatocellular carcinoma and breast cancer." (PMID 38978058, 2024). "We suggested that CDCA5 promoted progression of breast cancer via CDCA5/FOXM1/Wnt axis, CDCA5 might serve as a novel therapeutic target for breast cancer treatment." (PMID 38978058, 2024). "Moreover, FOXM1 knockdown reversed the inhibitory effects of CDCA5 on cell apoptosis in both breast cancer cell lines (p < 0.01)." (PMID 38978058, 2024). "On the other hand, it was demonstrated that CDCA5 knockdown could dramatically inhibit cell proliferation, migration and in vivo tumorigenesis in breast cancer." (PMID 38978058, 2024). "In recent years, CDCA5 was reported to function as a tumor promoter in various tumors, including bladder cancer, hepatocellular carcinoma, gastric cancer and esophageal squamous cell carcinoma, as well as the breast cancer." (PMID 38978058, 2024). "Here, the function and regulation mechanism of CDCA5 in breast cancer were explored." (PMID 38978058, 2024). "Additionally, we revealed that the Wnt/β-catenin signaling pathway was required for CDCA5 induced progression of breast cancer." (PMID 38978058, 2024). "Similarly, our results indicated that CDCA5 knockdown significantly decreased cell viability, colony formation, cell migration and promoted cell apoptosis in breast cancer." (PMID 38978058, 2024). "Moreover, in the breast cancer microenvironment, we found that CDCA5 is mainly expressed in malignant cells, proliferation T cells, and neutrophils." (PMID 37287817, 2023). "Moreover, we found that CDCA5 was upregulated in breast cancer cell lines, especially in MCF-7 and MDA-MB-231." (PMID 37287817, 2023). "We investigated the CDCA5 level in primary and metastatic breast cancer tissue further." (PMID 37287817, 2023). "We found a higher CDCA5 expression level in tissue and cells of breast cancer." (PMID 37287817, 2023). "CDCA5 was shown to be elevated in breast cancer tissue and cell lines in our investigation." (PMID 37287817, 2023). "The result showed that the primary breast cancer tissue had a lower DNA methylation level of CDCA5 compared with the normal tissue, which might partly explain the high CDCA5 expression in breast cancer." (PMID 37287817, 2023). "Transwell assays showed that the knockdown of CDCA5 might inhibit breast cancer cell invasion and migration ability." (PMID 37287817, 2023). "CDCA5 expression was shown to be greater in breast cancer tissue and cells." (PMID 37287817, 2023). "Moreover, we performed a ROC curve analysis to assess the prediction efficacy of CDCA5 on breast cancer." (PMID 37287817, 2023). "This study aims to assess the prognostic and biological value of CDCA5 in breast cancer (BC)." (PMID 36428736, 2022). "In conclusion, the current study showed that CCNE2, CDCA5, RAD51, TCF19, KNTC1, MCM10, and NEIL3 might contribute to EPT-related tumorigenesis in breast cancer, with CCNE2 might be a sensitive risk indicator of breast cancer risk in women using MHT." (PMID 36233194, 2022). "However, the role of CDCA5 has been confirmed in other cancers including hepatocellular cancer, breast cancer, gastric cancer, and colorectal cancer." (PMID 32149105, 2020). "On the whole, CDCA5 could be considered as a target for breast cancer, particularly invasive ductal breast carcinoma." (PMID 29467944, 2018). "Therefore, we assumed that Wnt/β-catenin signaling may be essential for CDCA5-mediated breast cancer progression." (PMID 38978058, 2024).
breast carcinoma (continued). "Moreover, new data suggested that upregulation of CDCA5 is correlated with prognosis of cancers and may be an independent predictor of cancer outcome, including breast cancer." (PMID 38978058, 2024). "Therefore, we showed that CDCA5 acted as a tumor promoter in breast cancer progression." (PMID 38978058, 2024). "However, whether Wnt/β-catenin signaling was required for CDCA5 mediated breast cancer progression was still unclear." (PMID 38978058, 2024). "CDCA5 might become a potential therapeutic target for breast cancer treatment." (PMID 38978058, 2024). "Additionally, CDCA5 was also involved in cell cycle control in breast cancer." (PMID 38978058, 2024). "However, few studies have examined the function of CDCA5 in breast cancer up to this point." (PMID 37287817, 2023). "In breast cancer, TIM and CDCA5 activate mTORC1/PI3K/AKT signaling, suppressing apoptosis while enhancing glycolysis through GLUT1/4 upregulation and HIF1α/c-Myc-mediated glycolytic enzyme synthesis." (PMID 41009376, 2025). "All together, we demonstrated that CDCA5 facilitated cell proliferation and migration, inhibited cell apoptosis via targeting FOXM1 in breast cancer." (PMID 38978058, 2024). "Mechanistically, through stabilizing CDCA5, TPI1 activates PI3K/AKT/mTOR pathway, which in turn promotes breast cancer metastasis and glycolysis." (PMID 35509067, 2022). "CDCA3, CDCA5, and CDCA8 are overexpressed and function as oncogenes in HCC and gastric and breast cancer." (PMID 34660326, 2021). "By analyzing the various tumor subtypes and cell lines of breast cancer, we found evidence for CDCA3, CDCA5, and CDCA8 involvement in breast cancer, resulting in an overall poor prognosis." (PMID 29467944, 2018). "In a similar expression pattern to CDCA3 and CDCA5, a high expression level of CDCA8 also correlated with a bad prognosis for breast cancer patients with a shorter RFS." (PMID 29467944, 2018). "Although bioinformatics has initially identified the abnormal upregulation of CDCA5 in breast cancer, the specific function and mechanism had not yet been elucidated." (PMID 38978058, 2024). "In addition, we found that the E2F1 was recruited to the FOXM1 promoter region, indicating that CDCA5 was capable to affect FOXM1 expression via binding to E2F1, thereby promoting in the progression of breast cancer." (PMID 38978058, 2024). "Also, we found a diverse expression pattern of CDCA5 in different subtypes of breast cancer, including luminal, HER2-enriched, basal-like, and normal-like breast cancer." (PMID 37287817, 2023). "Of these nodes, CDCA5 was the second significant node and has not been fully explored in breast cancer, therefore arousing our interest." (PMID 37287817, 2023). "It was reported that CDCA5 was a negative prognostic marker in multiple cancers, including breast cancer, colorectal cancer, and hepatocellular carcinoma." (PMID 36233194, 2022). "Altogether, these findings suggested CDCA3, CDCA5, and CDCA8 could have a high potency as targeted breast cancer therapies." (PMID 29467944, 2018). "Therefore, we suggested that CDCA5 promoted progression of breast cancer via CDCA5/FOXM1/Wnt axis for the first time, CDCA5 may serve as a novel therapeutic target for breast cancer treatment." (PMID 38978058, 2024). "At present, the role of CDCA5 in breast cancer cells has not been revealed." (PMID 35726220, 2022).